DUX4 (double homeobox 4)
Description:
[Isoform 1]: Transcription factor that is selectively and transiently expressed in cleavage-stage embryos. Binds to double-stranded DNA elements with the consensus sequence 5'-TAATCTAATCA-3'. Binds to chromatin containing histone H3 acetylated at 'Lys-27' (H3K27ac) and promotes deacetylation of H3K27ac. In parallel, binds to chromatin that lacks histone H3 acetylation at 'Lys-27' (H3K27ac) and recruits EP300 and CREBBP to promote acetylation of histone H3 at 'Lys-27' at new sites. Involved in transcriptional regulation of numerous genes, primarily as transcriptional activator, but also mediates repression of a set of target genes. Promotes expression of ZSCAN4 and KDM4E, two proteins with essential roles during early embryogenesis. Promotes nuclear translocation of CTNNB1/beta-catenin and its subsequent activation of target genes. Heterologous expression in cultured embryonic stem cells mediates transcription of HERVL retrotransposons and transcripts derived from ACRO1 and HSATII satellite repeats. May activate expression of PITX1. May regulate microRNA (miRNA) expression. Inappropriate expression can inhibit myogenesis and promote apoptosis. [Isoform 2]: Probably inactive as a transcriptional activator, due to the absence of the C-terminal region that is important for transcriptional activation. Can inhibit transcriptional activation mediated by isoform 1. Heterologous expression of isoform 2 has no deleterious effect on cell survival.
Synonyms: DUX4L
Tractability: No criterion of Open Targets' tractability assessment is met for any kind of drug.
Gene: Protein-coding gene on chromosome 4 (190,173,774 to 190,185,942, forward strand). Ensembl gene ENSG00000260596.
Subcellular location: Nucleus (Isoform 1); Cytoplasm; Nucleus (Isoform 2)
Subcellular location (Human Protein Atlas): Nucleoli; Nucleoplasm; Cytosol; Golgi apparatus
Pathways (Reactome):
Developmental Biology: Zygotic genome activation (ZGA)
Gene Ontology:
Molecular function: DNA-binding transcription activator activity, RNA polymerase II-specific; protein binding; RNA polymerase II cis-regulatory region sequence-specific DNA binding; sequence-specific double-stranded DNA binding; transcription cis-regulatory region binding; DNA-binding transcription factor activity, RNA polymerase II-specific; RNA polymerase II transcription regulatory region sequence-specific DNA binding; DNA binding
Biological process: apoptotic process; negative regulation of cell population proliferation; negative regulation of G0 to G1 transition; positive regulation of transcription by RNA polymerase II; regulation of transcription by RNA polymerase II
Cellular component: cytoplasm; nuclear membrane; nucleolus; nucleoplasm; nucleus
Homologues: Orthologues: macaque d4Z4 (81% identical), rat Dux4 (26% identical), mouse Duxbl1 (25% identical), tropical clawed frog mix1 (14% identical), zebrafish mxtx2 (13% identical), zebrafish mxtx1 (12% identical). Paralogues in human: DUXB (19% identical), PAX7 (18% identical), PAX3 (17% identical), ARX (15% identical), OTP (15% identical), OTX1 (15% identical), NOBOX (14% identical), OTX2 (14% identical), UNCX (14% identical), RAX (13% identical), CRX (13% identical), PAX6 (13% identical), and 38 more.
Diseases named in the same sentence as DUX4 in open-access papers:
DUX4 is named in the same sentence as 119 diseases in open-access papers, as found by Europe PMC text mining. Sharing a sentence is not in itself a finding about the gene and the disease. The quoted sentences say what the papers report.
facioscapulohumeral muscular dystrophy (141 papers, 2009 to 2026). An autosomal dominant disorder affecting the skeletal muscles of the face, scapula, and upper arm. "Facioscapulohumeral muscular dystrophy (FSHD) is caused by aberrant expression of the double homeobox transcription factor DUX4 in skeletal muscle." (PMID 41510809, 2026). "Facioscapulohumeral muscular dystrophy (FSHD) is an autosomal dominant muscular disease in which genetic mutations activate DUX4 expression in skeletal muscle." (PMID 41994867, 2026). "Facioscapulohumeral muscular dystrophy (FSHD) is caused by aberrant expression of double homeodomain protein 4 (DUX4)." (PMID 41536811, 2026). "In contrast, Facioscapulohumeral muscular dystrophy (FSHD) is associated with epigenetic de-repression of the DUX4 (double homeobox 4) gene, which leads to aberrant expression of the transcription factor DUX4 and cytotoxicity in skeletal muscle cells." (PMID 40868246, 2025). "Facioscapulohumeral muscular dystrophy (FSHD) is an autosomal dominant myopathy caused by aberrant expression of the DUX4 retrogene, and it affects skeletal muscles primarily in the face, shoulder, and limbs." (PMID 40909533, 2025). "DUX4 came to prominence during the search for the genetic cause of facioscapulohumeral muscular dystrophy (FSHD)." (PMID 40855454, 2025). "Aberrant expression of DUX4 in skeletal muscle is linked to facioscapulohumeral muscular dystrophy (FSHD)." (PMID 40422198, 2025). "DUX4 is the biomarker typically associated with a form of muscular dystrophy, namely facioscapulohumeral muscular dystrophy (FSHD)." (PMID 39123408, 2024). "Facioscapulohumeral muscular dystrophy (FSHD) is a progressive myopathy caused by the aberrant increased expression of the DUX4 retrogene in skeletal muscle cells." (PMID 38340007, 2024). "Facioscapulohumeral muscular dystrophy (OMIM #158900 & #158901) is a heterogeneous disorder caused by misexpression of the transcription factor DUX4 in skeletal muscle." (PMID 37380887, 2023). "Facioscapulohumeral muscular dystrophy (FSHD) is caused by the aberrant expression of the double homeobox 4 (DUX4) gene." (PMID 37511653, 2023). "Normally, DUX4 is expressed only in the embryonic period, whereas inadequate DUX4 repression in the postnatal period is associated with progressive muscle wasting and weakness (facioscapulohumeral muscular dystrophy)." (PMID 35784464, 2022). "Expression of DUX4-fl in somatic tissue is observed in facioscapulohumeral muscular dystrophy (FSHD) and has been revealed to be pathogenic." (PMID 34854471, 2022). "Facioscapulohumeral muscular dystrophy is a common genetic disease of muscle affecting approximately 1 in 8300 individuals, and is caused by failure of silencing of the DUX4 gene." (PMID 35216102, 2022). "Abnormal expression in skeletal muscle of the double homeobox transcription factor DUX4 underlies pathogenesis in facioscapulohumeral muscular dystrophy (FSHD)." (PMID 35191484, 2022). "Facioscapulohumeral muscular dystrophy (FSHD) is a genetic disease associated with ectopic expression of the DUX4 gene in skeletal muscle." (PMID 35621301, 2022). "Facioscapulohumeral muscular dystrophy (FSHD) is caused by misexpression of the DUX4 transcription factor in skeletal muscle that results in transcriptional alterations, abnormal phenotypes and cell death." (PMID 36196640, 2022). "Misexpression of DUX4 due to a failure in epigenetic repressive mechanisms underlies facioscapulohumeral muscular dystrophy (FHSD), a complex muscle disorder that thus far remains untreatable." (PMID 35176052, 2022). "Facioscapulohumeral muscular dystrophy (FSHD) type 1 is an autosomal dominant condition caused by mutations in DUX4." (PMID 33827624, 2021). "Facioscapulohumeral muscular dystrophy is a myopathy caused by aberrant de-repression of the DUX4 gene." (PMID 34880230, 2021). "Human SH regions also contain various genes, such as DUX4 (associated with facioscapulohumeral muscular dystrophy) and olfactory receptor genes." (PMID 33504776, 2021).
facioscapulohumeral muscular dystrophy (continued). "Facioscapulohumeral muscular dystrophy (FSHD) is a potentially devastating myopathy caused by de-repression of the DUX4 gene in skeletal muscles." (PMID 34880230, 2021). "DUX4 is a double homeobox transcription factor that when misexpressed in skeletal muscle promotes a toxic cellular environment and causes facioscapulohumeral muscular dystrophy (FSHD)." (PMID 34884532, 2021). "Facioscapulohumeral muscular dystrophy (FSHD) is caused by a complex epigenetic mechanism finally leading to the misexpression of DUX4 in skeletal muscle." (PMID 33396627, 2020). "DUX4 is the causative gene for facioscapulohumeral muscular dystrophy (FSHD), the third most common muscular dystrophy." (PMID 33173118, 2020). "Facioscapulohumeral muscular dystrophy (FSHD) is a skeletal muscle disorder that is caused by derepression of the transcription factor DUX4 in skeletal muscle cells." (PMID 33004076, 2020). "Facioscapulohumeral muscular dystrophy (FSHD) is a dominantly-inherited progressive muscular dystrophy caused by de-repression of the DUX4 gene, which causes disease by a toxic-gain-of-function." (PMID 31506080, 2019). "DUX4 is a transcription factor whose misexpression in skeletal muscle causes facioscapulohumeral muscular dystrophy (FSHD)." (PMID 30644821, 2019). "Aberrant expression of the full-length isoform of the double homeobox protein DUX4 (DUX4-FL), particularly in skeletal muscle, appears to underlie pathogenesis in facioscapulohumeral muscular dystrophy (FSHD)." (PMID 29618456, 2018). "Aberrant expression of the full-length isoform of DUX4 (DUX4-FL) appears to underlie pathogenesis in facioscapulohumeral muscular dystrophy (FSHD)." (PMID 29618456, 2018). "Failure of this repression causes facioscapulohumeral muscular dystrophy (FSHD) due to mis-expression of DUX4 in skeletal muscle." (PMID 29533181, 2018). "Facioscapulohumeral muscular dystrophy is a myopathy linked to ectopic expression of the DUX4 transcription factor." (PMID 29255294, 2017). "The goal of the study is to identity proteins, which interact with the promoter region of double homeobox protein 4 (DUX4) gene known to be causative for the autosomal dominant disorder Facioscapulohumeral Muscular Dystrophy (FSHD)." (PMID 27722032, 2016). "Facioscapulohumeral muscular dystrophy (FSHD) is generally considered to be caused by the contraction of D4Z4 repeats subsequently leading to the activation of a transcription factor DUX4 in skeletal muscle." (PMID 27547731, 2015). "On a larger scale, contractions of the D4Z4 macrosatellite that contains the DUX4 gene, in combination with a permissive haplotype background, underlie facioscapulohumeral muscular dystrophy (FSHD) [reviewed in 40]." (PMID 24945355, 2014). "DUX4 is normally expressed in the testis and epigenetically repressed in somatic tissues, but its variegated de-repression in muscle cells causes facioscapulohumeral muscular dystrophy (FSHD)." (PMID 24278031, 2013). "Facioscapulohumeral muscular dystrophy (FSHD) is caused by mutations that decrease the epigenetic repression of DUX4 in somatic tissues and result in mis-expression of this transcription factor in skeletal muscle." (PMID 24278031, 2013). "DUX4 constitutes a major candidate pathogenic protein for facioscapulohumeral muscular dystrophy (FSHD), the third most common form of inherited myopathy." (PMID 24116060, 2013). "Facioscapulohumeral Muscular Dystrophy (FSHD) is thought to be caused by aberrant production of a protein called Double Homeobox 4 (DUX4)." (PMID 22536400, 2012). "Facioscapulohumeral muscular dystrophy (FSHD) is linked to deletions in 4q35 within the D4Z4 repeat array in which we identified the double homeobox 4 (DUX4) gene." (PMID 22053214, 2011).
facioscapulohumeral muscular dystrophy (continued). "The DUX4 gene, located within repetitive subtelomeric arrays on chromosomes 4 and 10, plays a critical role in early embryogenesis and has been implicated in several human diseases, including facioscapulohumeral muscular dystrophy (FSHD) and cancer." (PMID 40940582, 2025). "Facioscapulohumeral muscular dystrophy (FSHD) is caused by the epigenetic derepression of the 4q-linked D4Z4 macrosatellite repeat resulting in inappropriate expression of the D4Z4 repeat-encoded DUX4 gene in skeletal muscle." (PMID 37380887, 2023). "Loss of silencing of the DUX4 gene on chromosome 4 causes facioscapulohumeral muscular dystrophy." (PMID 30446688, 2018). "Facioscapulohumeral muscular dystrophy (FSHD) is caused by epigenetic dysregulation of the disease locus, leading to pathogenic misexpression of DUX4 in skeletal muscle." (PMID 41889948, 2026). "Facioscapulohumeral muscular dystrophy (FSHD) is an autosomal dominant myopathy caused by aberrant expression of the double homeobox 4 (DUX4) retrogene, affecting skeletal muscles primarily in the face, shoulder and limbs." (PMID 41944163, 2026). "Misexpression of DUX4 is particularly toxic to muscle tissue and is etiologically linked to facioscapulohumeral muscular dystrophy (FSHD)." (PMID 41211819, 2025). "Facioscapulohumeral muscular dystrophy (FSHD) is a genetic muscle disease caused by ectopic expression of the toxic protein DUX4, resulting in muscle weakness." (PMID 40591405, 2025). "Disruption of this silencing mechanism is linked to facioscapulohumeral muscular dystrophy (FSHD), a genetic myopathy caused by aberrant expression of DUX4 in skeletal muscle cells." (PMID 40422198, 2025). "Facioscapulohumeral muscular dystrophy (FSHD) is caused by sporadic misexpression of the transcription factor double homeobox 4 (DUX4) in skeletal muscles." (PMID 39556762, 2025). "Facioscapulohumeral muscular dystrophy (FSHD) is a genetic muscular dystrophy caused by the misexpression of the DUX4 retrogene in skeletal muscles." (PMID 39391391, 2024). "FacioScapuloHumeral muscular Dystrophy (FSHD) is one of the most prevalent inherited muscle disorders and is linked to the inappropriate expression of the DUX4 transcription factor in skeletal muscles." (PMID 38542301, 2024). "Ectopic expression of DUX4 due to hypomethylation of the D4Z4 repeat array on permissive chromosome 4q35 alleles is associated with facioscapulohumeral muscular dystrophy (FSHD)." (PMID 39273067, 2024). "Facioscapulohumeral muscular dystrophy (FSHD) is caused by the epigenetic de-repression of the double homeobox 4 (DUX4) gene, leading to asymmetric muscle weakness and atrophy that begins in the facial and scapular muscles and progresses to the lower limbs." (PMID 39594549, 2024). "In adult somatic cells, DUX4 expression is silenced and its activation in adult muscle cells causes the genetic disorder Facioscapulohumeral Muscular Dystrophy (FSHD)." (PMID 38168299, 2023). "Mis-expression of DUX4 in skeletal muscle is the cause of facioscapulohumeral muscular dystrophy (FSHD), the third most prevalent human muscular dystrophy." (PMID 37092726, 2023). "DUX4 is also the causative gene of facioscapulohumeral muscular dystrophy (FSHD), a complex genetic disorder that results in epigenetic derepression of the DUX4 locus in skeletal muscle and progressive muscle atrophy." (PMID 37747887, 2023). "Facioscapulohumeral muscular dystrophy (FSHD) is an incurable myopathy linked to the over-expression of the myotoxic transcription factor DUX4." (PMID 37184373, 2023). "Facioscapulohumeral muscular dystrophy (FSHD) is an autosomal dominant disorder caused by the aberrant expression of the double homeobox 4 (DUX4) gene, resulting in progressive muscle loss." (PMID 37511653, 2023). "DUX4c is highly similar to DUX4 whose misexpression in skeletal muscle causes facioscapulohumeral muscular dystrophy (FSHD)." (PMID 36882853, 2023).
facioscapulohumeral muscular dystrophy (continued). "DUX4 is a key regulator of zygotic genome activation in human embryos, whereas misexpression of DUX4 causes facioscapulohumeral muscular dystrophy (FSHD) and is associated with MHC-I suppression and immune evasion in cancer." (PMID 37747887, 2023). "Aberrant expression in skeletal muscle of DUX4, a double homeobox transcription factor, underlies pathogenesis in facioscapulohumeral muscular dystrophy (FSHD)." (PMID 35538497, 2022). "Additionally, mouse Dux is myotoxic and shares a partial functional homology with its human paralog DUX4, the aberrant expression of which is linked to facioscapulohumeral muscular dystrophy, which further confirms the conserved roles of Dux/DUX4 in gene regulation." (PMID 35216182, 2022). "Facioscapulohumeral muscular dystrophy (FSHD) is a genetically dominant progressive myopathy caused by improper silencing of the DUX4 gene, leading to fibrosis, muscle atrophy, and fatty replacement." (PMID 36056021, 2022). "Facioscapulohumeral muscular dystrophy (FSHD) is caused by misexpression of DUX4 in skeletal myocytes." (PMID 34338285, 2021). "Facioscapulohumeral muscular dystrophy (FSHD) is caused by chromatin relaxation of the D4Z4 repeat resulting in misexpression of the D4Z4-encoded DUX4 gene in skeletal muscle." (PMID 34484861, 2021). "Facioscapulohumeral muscular dystrophy (FSHD) is caused by expression of the DUX4 gene in skeletal muscle because of D4Z4 macrosatellite repeat chromatin de-repression." (PMID 33067535, 2020). "All types of facioscapulohumeral muscular dystrophy (FSHD) are caused by the aberrant activation of the somatically silent DUX4 gene, the expression of which initiates a cascade of cellular events ultimately leading to FSHD pathophysiology." (PMID 32278354, 2020). "Facioscapulohumeral muscular dystrophy (FSHD) is caused by the expression of DUX4 in skeletal muscles." (PMID 33067535, 2020). "Among these, we identified DUX4, a potent transcription factor that causes facioscapulohumeral muscular dystrophy (FSHD)." (PMID 26816005, 2016). "Facioscapulohumeral muscular dystrophy (FSHD) is a genetic disease caused by ectopic expression of an unusual double homeodomain transcription factor, DUX4." (PMID 26978271, 2016). "Facioscapulohumeral muscular dystrophy (FSHD) is believed to be caused by aberrant expression of double homeobox 4 (DUX4) due to epigenetic changes of the D4Z4 region at chromosome 4q35." (PMID 26007167, 2015). "DUX4 is causally involved in the molecular pathogenesis of the neuromuscular disorder facioscapulohumeral muscular dystrophy (FSHD)." (PMID 21110847, 2010). "The polymorphic repeat also encodes a member of the DUX gene family termed DUX4 which is supposed to have a major impact on the etiology of FSHD (Facioscapulohumeral muscular dystrophy;), the third most common muscular dystrophy." (PMID 19404400, 2009). "DUX4 de-repression in muscle cells moreover drives cell death and the human disease, facioscapulohumeral muscular dystrophy (FSHD)." (PMID 41417901, 2025). "DUX4 has emerged as pivotal in the pathomechanisms of facioscapulohumeral muscular dystrophy (FSHD), a relatively common hereditary muscle wasting condition, although classified as a rare disease." (PMID 40855454, 2025). "It has been shown in the human disease facioscapulohumeral muscular dystrophy, that the natural loss of NMD through DUX4 overexpression leads to the production of truncated proteins normally inhibited by NMD activity." (PMID 41300748, 2025). "In humans, these consist of the three paralogues DUXA, DUXB and DUX4, of which only DUX4 has been extensively characterised due to its roles in facioscapulohumeral muscular dystrophy (FSHD) and multiple cancers." (PMID 40940582, 2025). "Mutations in SMCHD1 cause facioscapulohumeral muscular dystrophy (FSHD), by overexpressing DUX4 in muscle cells." (PMID 38809976, 2024).